SALL4 (spalt like transcription factor 4)
Diseases named in the same sentence as SALL4 in open-access papers (continued):
Sharing a sentence is not in itself a finding about the gene and the disease.
cancer (continued). "In the present study, a total of 1,815 GC patients who underwent radical resection at Peking Cancer Hospital were included consecutively from 2015 to 2018, confirming the prognostic value of SALL4 and validating by data from TCGA and GEO." (PMID 33644042, 2021). "Our analysis of ALDH1 and SALL4 expression suggested that cancer cells in clusters and single cells have different properties of tumorigenicity, but the clinical significance of cluster formation in MPE is unclear." (PMID 34441397, 2021). "Blocking SALL4/HDAC interaction with a peptide derived from the amino-terminal 12-amino-acid sequence of SALL4 led to higher PTEN expression and an antiproliferative effect on SALL4-expressing cancer cells." (PMID 34944911, 2021). "For more comprehensive information on SALL4 and miRNAs and the strategies targeting the miR/SALL4 axis in cancer, see a recent review by Liu J and collaborators." (PMID 34944911, 2021). "Deregulation of SALL4 was found in many different types of cancer such as leukemia, glioma, breast cancer, germ cells tumor, and colorectal cancer." (PMID 35008527, 2021). "ALDH1-positive and SALL4-positive cancer cells in MPE were detected in 30 (65.2%) and 21 samples (45.7%), respectively." (PMID 34441397, 2021). "In this systematic review, we summarize the current knowledge of SALL4 and miRNA functions in development and cancer, with a focus on the Let-7/Lin28 axis." (PMID 34573282, 2021). "For instance, in some certain cancer cells, Myc is upregulated through directly transcriptional activation by SALL4." (PMID 32098783, 2020). "In this article, we make use of a Drosophila genetic model for epithelial tumor invasion to explore the molecular mechanism of SALL4 in cancer cell invasion and metastasis." (PMID 32098783, 2020). "This correlation indicates a contribution of MEIS1/SALL4 expression in operating cancer aggressiveness in ESCC." (PMID 32819319, 2020). "Aberrant expression of SALL4 observed in different types of cancers and disruption of multiple cellular tumorigenesis processes suggested a key stemness regulatory effect for SALL4." (PMID 32819319, 2020). "Restored SALL4 expression has been reported to be detectable in various tumors and exhibit oncogenic roles in cancer genesis and progression." (PMID 32513235, 2020). "By contrast, there is substantial evidence that SALL4 is highly upregulated in numerous human cancers and regulates multiple cellular processes responsible for cancer progression." (PMID 32098783, 2020). "The clinical significance of SALL4 in ccRCC patients and its important role in cancer genesis and progression will shed light on novel diagnosis and therapy for ccRCC patients in the future." (PMID 32513235, 2020). "SALL4 has emerged as a transcription factor governing multiple biologic processes in the initiation and development of human cancers." (PMID 32513235, 2020). "To elucidate SALL4 expression signatures in human malignancies, we conducted pan-cancer analysis of public TCGA datasets in UALCAN database." (PMID 32513235, 2020). "Generally, in cancerous tissues, the later cancer classification and stage were, the higher expression of SALL4 was." (PMID 30907073, 2019). "SALL4 is a vital factor in the development and prognosis of various cancers, but its role in radioresistance remains elusive." (PMID 30907073, 2019). "To verify the function of SALL4 in cancer progression, we provided evidence that lower proliferation ability was observed in SALL4 silencing NPC cells." (PMID 30907073, 2019). "Given the oncogenic role of SALL4 and its specific expression in a subset of cancers, its usefulness as a therapeutic target has been explored." (PMID 30989433, 2019). "We will investigate the downstream target genes of SALL4, to find out which genes are directly or indirectly taken part in the SALL4 regulation of NSCLC cancer stem cells." (PMID 29691367, 2018).
cancer (continued). "Previous studies have demonstrated that SALL4 is aberrantly expressed in a variety of human cancer types and significantly closely correlated with the prognosis of patients." (PMID 29691367, 2018). "In cancers where aberrantly reactivated, SALL4 has been associated with the expression of many stemness-related genes (i.e. OCT4, NANOG, c-Myc, and SOX2) conferring to the cancer cells self-renewal pluripotency abilities." (PMID 28160555, 2017). "Similar findings were obtained also considering the recurrence of cancer as outcome (26 cohorts [12, 14, 16, 17, 23, 25, 28 and the TCGA cohorts]; recurrence rate: 51.5% SALL4+ vs. 42.2% SALL4-; RR=1.25; 95% CI: 1.1-1.42, p=0.0006; I2=62%)." (PMID 28160555, 2017). "Specifically, in induced pluripotent stem (iPS) cells, in embryonal stem cells (ESCs), and in SALL4+ cancers, the expression of SALL4 has been related to the hypo-methylation of its promoter." (PMID 28160555, 2017). "Recently, a meta-analysis showed a possible correlation between SALL4 expression and poor prognosis in cancer patients." (PMID 28160555, 2017). "SALL4 characterizes a feature of drug resistance through the maintenance of side population cancer stem cells and affects the side population cells by regulation of ABC drug transport genes ABCG2 and ABCA3 in leukemic cells." (PMID 26935744, 2016). "In this study, we found that SALL4 was related to cancer stemness features, such as colony ability, chemoresistance and EMT phenotype." (PMID 27329034, 2016). "SALL4 is also aberrantly expressed in many cancers and correlates with poor prognosis, leading it to be heralded as a new cancer biomarker and potential therapeutic target." (PMID 27471257, 2016). "Sall4 is an essential transcription factor for early mammalian development and is frequently overexpressed in cancer." (PMID 27471257, 2016). "To search for potential existing drug(s) to treat SALL4-expressing cancers, we conducted Connectivity Map (cMap) analysis." (PMID 27705911, 2016). "The expression of SALL4 was significantly increased in cancer tissues compared to normal controls (p<0.0001), confirming our observation from the immunohistochemistry staining." (PMID 27705911, 2016). "The stem cell factor SALL4 (Sal-like protein 4) plays important roles in the development and progression of cancer." (PMID 27819668, 2016). "Individual cohorts have sporadically revealed the unfavorably prognostic role of SALL4 in certain types of cancer." (PMID 27007163, 2016). "While the development of SALL4-specific inhibitor(s) that mimic this SALL4 peptide is ongoing, we set out to search for existing drugs that can potentially treat SALL4-expressing cancers." (PMID 27705911, 2016). "Among the 133 ESCC cases, 102 (76.7 %) showed high level of SALL4 expression and 31 (23.3 %) showed low level of SALL4 expression in cancer tissues." (PMID 27329034, 2016). "Previous studies have revealed that HMGA2, SALL4 and Twist1 are involved in cancer stem cell self-renewal in different cell types." (PMID 25919570, 2015). "SALL4 is an important regulator of the stemness state and survival, not only in several types of normal stem cells, but also in cancer cells and possibly cancer stem cells." (PMID 23363002, 2013). "SALL4 is an important regulator not only of the stemness state and survival of several types of normal stem cells, but also the survival and expansion of cancer cells and possibly cancer stem cells." (PMID 23363002, 2013). "This led to our investigation of the implication of SALL4 in drug resistance and its role in side population (SP) cancer stem cells." (PMID 21526180, 2011). "Although Sall4’s role in promoting Wnt/β-catenin signaling is well documented in tissue stem-like cells, including in various cancers, its interactions within cardiac biology remain underexplored, presenting a critical area for future research in cardiac regeneration and therapy." (PMID 39936946, 2025).
cancer (continued). "Notably, SALL4 expression has been linked to proliferative, invasive, and antiapoptotic effects through activation of the PI3K/AKT pathway in various cancer stem-like cells." (PMID 39936946, 2025). "Two additional investigations revealed that exosomes derived from BMSCs, which contain miR-15a and miR-338-3p, inhibited growth, mobility, and cancer cell invasion by reducing the expression of spalt-like transcription factor 4 (SALL4) and E26 transformation-specific-1 (EST1), respectively." (PMID 41244150, 2025). "Sall4 as a pivotal transcription factor has been extensively studied across diverse biological processes, including stem cell biology, embryonic development, hematopoiesis, tissue stem/progenitor maintenance, and the progression of various cancers." (PMID 39936946, 2025). "Additionally, this genetic silencing of SALL4-B resulted in reduced cell viability and impaired anchorage-independent growth, highlighting SALL4-B’s role in supporting the survival and proliferative capacity of cancer cells driven by SALL4 expression." (PMID 39905414, 2025). "Recent studies have shed light on how SALL4 contributes to PI3K/AKT pathway activation in cancer." (PMID 41163374, 2025). "Consequently, SALL4 has been proposed as a potential biomarker for early cancer diagnosis and as a therapeutic target for treatment." (PMID 41163374, 2025). "Cytoplasmic expression of SALL4 was also reported among other types of cancer." (PMID 39905414, 2025). "In addition to tumorigenesis, metastasis, and drug resistance of cancers, SALL4 transcriptionally regulates the expression of VEGF to promote angiogenesis." (PMID 38584262, 2024). "Moreover, by using the same evaluation criteria, we identify new biomarkers whose impact on drug response spans multiple cancers, including SALL4, B2M, BAP1, CCDC6, ERBB4, FOXA1, GRIN2A, and PTPRT." (PMID 39083502, 2024). "Additional research in this area could potentially provide novel ideas and perspectives for SALL4-targeting cancer treatment." (PMID 39001344, 2024). "Understanding and studying the mechanisms of SALL4 in cancer may help to develop new therapeutic perspectives for rare cancer conditions." (PMID 39001344, 2024). "In addition to proteins known to directly bind REN, such as Cul3, RBX1, and KCTD15, we recovered various potential REN interactors including SALL4, a cell stemness regulator aberrantly activated in several types of human cancers." (PMID 38062245, 2024). "For all these reasons, SALL4 is emerging as attractive therapeutic target in cancer." (PMID 38062245, 2024). "Finally, our results identified a molecular network controlling SALL4 expression in PDAC‐associated CAF and correlated with cancer stemness properties and worse clinical outcomes." (PMID 36587397, 2023). "Two other studies also demonstrated that the BMSC-derived exosomes miR-15a and miR-338-3p delayed the proliferation, migration and invasion of cancer cells by downregulating spalt-like transcription factor 4 (SALL4) and E26 transformation specific-1 (EST1), respectively." (PMID 36142881, 2022). "Thus, SALL4-positive cancer cells possess a latent capacity for the Warburg effect, but this latent capacity is suppressed in the steady state." (PMID 35216168, 2022). "Other Wnt target genes include those of MMPs and VEGF, which are known to be involved in neovascularization and interact with cancer stem cell markers such as Sal-like protein 4 (SALL4), epithelial cell adhesion molecule (EpCAM), and the adhesion molecule E-cadherin." (PMID 35053606, 2022). "Furthermore, detailed literature review suggests that SALL4 expression increases both mortality and recurrence of cancer, and suggests SALL4 as an important prognostic marker." (PMID 35482646, 2022). "Overall, SALL4 can interact with other transcription factors to regulate the Notch pathway or directly interact with Notch and then impact the progression and self-renewal capacity of various cancer cells." (PMID 35216168, 2022).
cancer (continued). "Recent findings have shown that SALL4 is reexpressed in cancer." (PMID 35692499, 2022). "Moreover, repression of E-cadherin (CDH1) by SALL4 modulates cell dispersion in basal-like cancer types." (PMID 36010677, 2022). "SALL4 upregulates Gli1 that is known for its role in cancer development." (PMID 36010677, 2022). "In addition to expression and function in mouse development and regeneration, SALL4 expression is reported in many types of human cancers." (PMID 35482646, 2022). "SALL4 is a potential target for the diagnosis and treatment of cancer." (PMID 35216168, 2022). "The Sangerbox database was applied to examine SALL4 in various cancers." (PMID 35692499, 2022). "Three different approaches are investigated for targeting SALL4 in cancer cells." (PMID 36010677, 2022). "Sall4 expression patterns and functional studies suggest that Sall4 is necessary in various tissues and organs during embryonic development, in adult germ cells, and contributes to pathological conditions such as cancer." (PMID 35482646, 2022). "Since zinc-finger transcription factor SALL4 is a stem cell factor triggering invasion and migration of cancer cells, it might contribute to a metastatic phenotype in high metabolic HCC tumors." (PMID 36612182, 2022). "Studies suggest that SALL4 functions in cancer survival, drug resistance, and metastasis." (PMID 35482646, 2022). "In addition, along with the advancement in technologies and our growing knowledge of gene regulation, there is an exciting new direction in cancer treatment by targeting TFs, including SALL4." (PMID 36010677, 2022). "In the past decade, research has suggested SALL4 may be a valuable biomarker or therapeutic target for a range of cancers." (PMID 36680176, 2022). "The transcription factor SALL4 has been related to aggressiveness and resistance therapy in cancer." (PMID 36362083, 2022). "The functional association of SALL4 with cancer incidence, progression, and metastasis suggests that SALL4-targeting could be effective in eradicating cancer cells." (PMID 36010677, 2022). "However, there is association between SALL4 and ALDH1 in other types of cancer by in-vitro and in-silico evidence." (PMID 35090523, 2022). "In recent years, SALL4 has emerged as a potential biomarker in many cancers, including BC." (PMID 36362083, 2022). "Up-regulation of SALL4 promotes proliferation, metastasis, and drug resistance of cancer cells." (PMID 34573282, 2021). "Induction of EMT via the deregulation of LINC-ROR may activate the expression of stemness marker, SALL4, as a TF with an oncogenic role in GC, to promote cancer phenotype." (PMID 33745265, 2021). "SALL1, SALL2, and SALL4 cancer-related isoforms have been reported." (PMID 34944911, 2021). "Previously, multiple strategies have been proposed to target SALL4 for cancer therapies." (PMID 34573282, 2021). "Besides, GSEA and WGCNA were applied to explore the SALL4-related cancer-promoting signaling pathways and gene modules." (PMID 33644042, 2021). "Previous studies have demonstrated the regulation of SALL4 overexpression in cancer." (PMID 33644042, 2021). "However, SALL4 is upregulated in this type of cancer, and its expression correlates with disease recurrence and decreased disease-free survival." (PMID 34944911, 2021). "Conversely, SALL4 overexpression promotes cancer metabolic phenotype which can be reversed by HK-2 knockdown suggesting that this glycolytic enzyme is a downstream effector of the transcriptional factor SALL4." (PMID 34249759, 2021). "However, further studies are necessary to explore the direct regulation of SALL4 by Let-7 family members in these cancer types." (PMID 34573282, 2021). "Most of them target SALL4, and some miRNAs are common among cancers." (PMID 34944911, 2021). "The transcription factor SALL4 has been extensively studied in human cancers." (PMID 32489324, 2020). "Given the aberrant expression in human cancers, SALL4 has been identified as a cancer biomarker." (PMID 32513235, 2020).
cancer (continued). "The results of bioinformatics analysis suggested that SALL4, which has been reported to function as an oncogene in many types of cancers, could be a potential target of miR-3622a-3p." (PMID 32719361, 2020). "This study revealed that SALL4 regulates CD44v expression via KHDRBS3 for stemness, which might contribute to understanding of the function of SALL4 on cancer stemness." (PMID 29356399, 2018). "Notably, these cancers exhibited the expression of pluripotency-related proteins, Sall4 and Lin28a, independently of OSKM transgene expressions." (PMID 29802314, 2018). "However, due to the lack of a comprehensive investigation of its prognostic value and to the different assessment techniques and protocols, the reliability of SALL4 as prognostic marker in cancer is still doubtful." (PMID 28160555, 2017). "Due to its prognostic value, SALL4 expression should be considered as potential marker in the next-generation histopathological diagnosis, hopefully by standardized IHC protocols, integrating cancer morphological features and molecular targets information." (PMID 28160555, 2017). "For the cancer recurrence, considering the available 4 studies and the 17 TCGA cohorts, a similar result was obtained confirming a worse prognostic role of SALL4+ (HR=1.52; 95% CI: 1.22-1.89, p=0.0002; I2=69%)." (PMID 28160555, 2017). "Recently, several studies have proposed SALL4 as possible prognostic marker for cancer." (PMID 28160555, 2017). "Our results revealed that SALL4 might serve as a functional marker for ESCC cancer stem cell, a crucial marker for prognosis and an attractive candidate for target therapy of ESCC." (PMID 27329034, 2016). "Up-regulating SALL4 in cancer cells can promote their proliferative and invasive abilities." (PMID 26935744, 2016). "SALL4 plays a role in multiple types of cancers and has been previously used as a CSC marker." (PMID 27148537, 2016). "Thus, it is reasonable that upregulation of SALL4 expression increased proliferation of cancer cells and enhanced the capacity of invasion and metastasis of cancer cells, subsequently promoted vascular invasion and nerve invasion in ICC." (PMID 26317546, 2015). "In support of this hypothesis, previous analysis of the SALL4/Bmi-1 regulatory pathway in cancer stem cells revealed the potential of this pathway as an attractive target for therapeutic intervention." (PMID 23363002, 2013). "SALL4 appears to involve the proliferation and the self-renewal of cancer cells." (PMID 22848863, 2012). "However, aberrant re‐expression of SALL4 has been observed in a wide range of cancers." (PMID 41163374, 2025). "Therefore, co-expression of SALL4/ALDH1A1 may serve as a potential prognostic biomarker of cancer progression in these cases." (PMID 35090523, 2022). "Moreover, they found the correlation of SALL4 expression with stemness of the cancer cells." (PMID 36010677, 2022). "Thus, an in-depth understanding and study of the functions and mechanisms of SALL4 in cancer may help develop novel strategies for cancer therapy." (PMID 35216168, 2022). "Furthermore, Sall4 is specifically expressed by cancer cells in choriocarcinoma." (PMID 34680590, 2021). "With the advancement of tissue specific microRNA delivery mechanisms and the expansion of literature on SALL4-targeting microRNAs in various cancer types, we propose that targeting SALL4 with microRNA-based therapeutics may be a new direction in overcoming SALL4 reactivation." (PMID 34573282, 2021). "However, in many cancers including blood cancers and solid tumors, SALL4 expression is restored." (PMID 32489324, 2020). "Thus, SALL4 is currently considered as an emerging cancer biomarker candidate." (PMID 29593314, 2018). "However, there is increasing evidence showing that SALL4 expression is re-stored in cancer." (PMID 27819668, 2016). "SALL4 mRNA could be used as a marker for the diagnosis of different types of cancers." (PMID 28959334, 2016).